TLR2 (toll like receptor 2)
Diseases named in the same sentence as TLR2 in open-access papers (continued):
Sharing a sentence is not in itself a finding about the gene and the disease.
synucleinopathies (13 papers, 2018 to 2025). "A key role has been suggested for TLR-2 in synucleinopathies, in the CNS and periphery associated with various biological activities." (PMID 36982988, 2023). "TLRs are integral to microglia, and the microglial expression of the TLR2/1 heterodimer is specifically implicated in synucleinopathy pathogenesis." (PMID 29780321, 2018). "Furthermore, TLR2 has been known to be associated with multiple neurodegenerative diseases such as synucleinopathies and Alzheimer’s disease (AD)." (PMID 41258081, 2025). "Toll-like receptor 2 (TLR2), a pattern recognition immune receptor, has been implicated in the pathogenesis of synucleinopathies because TLR2 is elevated in the brains of patients with PD and TLR2 is a mediator of the neurotoxic and pro-inflammatory effects of extracellular α-synuclein aggregates." (PMID 30092810, 2018). "Neuronal TLR2 has also been shown to mediate neuron-to-neuron transmission of α-syn, implicating it in the propagation of synucleinopathies." (PMID 38681666, 2024). "It has been suggested that TLR2 is upregulated in the pathogenesis of synucleinopathies in the brains of PD patients, thereby establishing TLR2 as a mediator of not only pro-inflammatory but also neurotoxic effects of extracellular α-synuclein aggregates." (PMID 37569837, 2023). "The authors proposed targeting TLR-2 as a promising immunotherapeutic approach to synucleinopathies." (PMID 36081661, 2022). "TLR-2, involved in the reversible neuronal dysfunction and glial activation induced by α-synOs is consistent with findings suggesting a key role for TLR-2 in synucleinopathies." (PMID 36081661, 2022). "Before testing wtTIDM peptide for controlling α-synucleinopathy, we monitored the level of TLR2 in the CNS of A53T mice." (PMID 34508096, 2021). "We have convincingly showed that both microglial inflammation and spreading of pathological α-syn happen simultaneously in the brain of different models of α-synucleinopathy and that TLR2 is capable of controlling both pathological events." (PMID 34508096, 2021). "This study proposes TLR2 immunotherapy as a novel therapeutic strategy for synucleinopathies of the aging population." (PMID 30092810, 2018). "In summary, we propose that TLR2 is a novel target for immunotherapy and a potentially viable therapeutic strategy for synucleinopathies of the aging population." (PMID 30092810, 2018). "α-synuclein high expresser mouse (α-Syn-tg; under mThy1 promoter, Line 61) was administrated with anti-TLR2 to examine that functional inhibition of TLR2 ameliorates neuropathology and behavioral defect in the synucleinopathy animal model." (PMID 30092810, 2018). "Within the field of synucleinopathy research, oligomeric forms of αSyn have been shown to directly interact with the TLR2/1 heterodimer and lead to a prototypical inflammatory response." (PMID 29780321, 2018). "However, it is also worth identifying more specific downstream targets for synucleinopathies considering TLR2 is the most upstream signaling receptor in these cells." (PMID 41258081, 2025). "Next, we investigated molecular mechanisms by which TLR2 is coupled to α-synucleinopathy." (PMID 34508096, 2021). "Overexpression of astroglial TLR2 significantly increased astroglial α-synuclein internalization as well as neuron-to-astrocyte α-synuclein transmission in in vitro synucleinopathy model system, while those were inhibited by anti-TLR2 treatment and TLR2 gene knockdown." (PMID 30092810, 2018). "Therefore, this review aims to focus on the relationship between the particulars of αSyn and the TLR2 signaling pathway with respect to their roles in synucleinopathy progression and recent advances in inhibiting the microglial inflammatory response." (PMID 29780321, 2018). "Delivery of TLR2 overexpression lentiviral vectors into mouse model of synucleinopathy." (PMID 30092810, 2018).
synucleinopathies (continued). "While for this study we focused on the effects of blocking TLR2 on glial and NFκB dependent neuro-inflammatory responses, in previous studies we investigated the pathological roles of TLR2 in neurons in in vitro and in vivo models of synucleinopathy." (PMID 30092810, 2018). "Therefore, we targeted TLR2 in in vivo and in in vitro models of synucleinopathy using a functional inhibitory antibody (T2.5)." (PMID 30092810, 2018). "Therefore, TLR2 and downstream signaling have been suggested a new therapeutic target for synucleinopathy." (PMID 30092810, 2018). "Hence, the benefits of TLR2 inhibition in synucleinopathies might be limited owing to its potential off-target effects." (PMID 41258081, 2025). "Therefore, TLR2 might be a viable target and TLR2 immunotherapy is a novel therapeutic strategy for synucleinopathies of the aging population." (PMID 30092810, 2018). "We have previously shown that TLR2 might mediate the neurotoxic and pro-inflammatory effects of α-synuclein oligomers and it has been recently reported that levels of TLR2 expression are increased in the brains of patients with synucleinopathy." (PMID 30092810, 2018). "Collectively, these results suggest that targeting TLR2 by immunotherapeutic approach decreased accumulation of neurotoxic α-synuclein aggregates and neuroinflammation, thereby ameliorating neurodegeneration and behavioral defects in an animal model of synucleinopathy." (PMID 30092810, 2018). "To further confirm the role of TLR2 signaling in the inflammation of the injured vagus nerve, we injected AAV-Cas9-TLR2 simultaneously in the vagus nerve of rats with α-synucleinopathy." (PMID 36788559, 2023). "Importantly, Toll-like-receptors 2 and 4 (TLR2 and TLR4) are considered crucial modulators of glial responses in a-synucleinopathies, as well as key players in aSyn phagocytosis." (PMID 34066733, 2021).
chorioamnionitis (12 papers, 2006 to 2025). A morphologic finding indicating inflammation of the fetal sac membranes. "In mice, advancing gestation is correlated with enhanced amniotic fluid expression of TLR2 and in humans TLR2 expression is increased in myometrium and fetal membranes in association with spontaneous term and preterm labour with evidence of chorioamnionitis." (PMID 29682558, 2018). "TLR2 tends to be highly expressed in the placentas of pregnant women with chorioamnionitis, suggesting a relationship between TLR2 and pregnancy failure." (PMID 34675905, 2021). "In cases with histological chorioamnionitis, however, significant TLR-2 expression was found in all the epidermal layers." (PMID 17064297, 2006). "In contrast, the majority of the epidermal keratinocytes in the basal through to the superficial layers were strongly immunopositive for TLR-2 in fetuses with histological chorioamnionitis." (PMID 17064297, 2006). "Spontaneous labor at term and preterm delivery with histologic chorioamnionitis, regardless of the membrane status (intact or ruptured), is associated with an increased expression of TLR-2 and TLR-4 in the fetal membranes." (PMID 22899878, 2012). "The spontaneous labor at term and preterm delivery with histologic chorioamnionitis, regardless of the membrane status (intact or ruptured), are associated with an increased expression of TLR-2 and -4 by the chorioamniotic membranes." (PMID 21122132, 2010). "The TLR2 expression was found to be polarized to the basal surface of amniotic epithelial cells in patients without chorioamnionitis, but this distribution was lost in the presence of inflammation." (PMID 21647232, 2011). "Researchers found that TLR2 expression was significantly higher in patients with chorioamnionitis than in those without this condition." (PMID 21647232, 2011). "The purpose of our study was to determine if the fetal skin develops an inflammatory response (dermatitis) and evaluate whether the expression of TLR-2 and TLR-4 is altered in cases of histological chorioamnionitis." (PMID 17064297, 2006). "TLR-2 immunoreactivity in the skin was stronger in fetuses with chorioamnionitis than in those without this condition." (PMID 17064297, 2006). "Significant TLR-2 immunoreactivity was found only in the keratinocytes in the superficial layer of the epidermis in cases without histological chorioamnionitis." (PMID 17064297, 2006). "At the maternal–fetal interface, chorioamnionitis activates innate immune pathways in the placenta and membranes via TLR2/TLR4 recognition of Gram-positive or Gram-negative pathogen-associated molecular patterns (PAMPs), triggering the MyD88–NF-κB signaling cascade." (PMID 41102816, 2025). "However, the expression of TLR-2 was significantly higher in the epidermis of fetuses with histological chorioamnionitis than in those without this condition." (PMID 17064297, 2006). "Given that TLR2 and TLR4 provide an innate immune response against gram-positive and gram-negative bacteria, one might assume that CB monocytes are capable of mounting particularly potent pro-inflammatory responses against pathogens frequently involved in chorioamnionitis and neonatal sepsis." (PMID 36902350, 2023). "The fetal skin expressed TLR-2 and TLR-4 in the epidermis regardless of histological chorioamnionitis status." (PMID 17064297, 2006).
dengue (12 papers, 2008 to 2025). "Another study indicated that TLR2 polymorphisms are associated with the severity of dengue virus infection, suggesting that genetic variations in TLR2 may impact the host’s ability to control viral replication." (PMID 41295183, 2025). "Research has shown that certain TLR2 variants may influence the immune response to viruses such as dengue and HIV, potentially affecting disease outcomes." (PMID 41295183, 2025). "Few functional polymorphisms of TLR2 gene such as Arg735Gln, and Pro 631 His are known,which alter the activity of receptor or impair receptor signalling, which in turn increases the susceptibility to dengue virus infection." (PMID 34602778, 2021). "This deviation could be due to racial and ethnic factors.The association of these polymorphisms to TLR2 with Dengue virus infection is reported for the first time in this study." (PMID 34602778, 2021). "Furthermore, dengue-infected hosts are more susceptible to sepsis, which could be due to early TLR2-dependent proinflammatory cytokine production." (PMID 34603272, 2021). "Altogether, our data provide evidence for the ability of TLR2 on monocytes to not only sense immature dengue particles but also regulate the subsequent inflammatory responses." (PMID 36240261, 2022). "Altogether, these results indicate that TLR2/TLR6/CD14- mediated sensing of immature dengue particles induces the production of TNF-α and IL-1β by monocytes." (PMID 36240261, 2022). "Altogether, these data underscore the pivotal role of monocyte expressed TLR2 in the sensing of immature dengue particles and subsequent modulation of inflammatory responses." (PMID 36240261, 2022). "Our in vitro infection model, however, did not address the infection enhancing or neutralizing effects of dengue-specific antibodies on TLR2-mediated immune responses." (PMID 32576819, 2020). "Altogether, our data show that TLR2 sensing of dengue virus infection induces production of inflammatory mediators, which in turn can activate endothelial cells." (PMID 32576819, 2020). "In the current study, dengue virus infection was found to activate and up-regulate TLR2 and TLR6 of human PBMC and DV NS1 protein was shown to be the viral protein responsible." (PMID 26226614, 2015). "Blocking of TLR2 and TLR6 also reduced the amount of IL-6 produced by PBMC during dengue virus infection, this suggested that TLR2 and TLR6 are activated during dengue virus infection and this activation led to increase in IL-6 secretion." (PMID 26226614, 2015). "CD14+ monocytes expressing TLR2 were reported by Azeredo and colleagues (2010) to be increased in peripheral blood of dengue patients." (PMID 26226614, 2015). "It was proposed that the overexpression of TLR2 in DCs and pDCs could contribute to severe forms of dengue." (PMID 35632732, 2022). "Furthermore, in acute dengue patients increased TLR2 expression on monocytes is predictive of severe disease development." (PMID 36240261, 2022). "The study not only demonstrated the importance of cross-talk between platelets and neutrophilic activation, but also shed light on the co-participation between different PRRs (CLRs and TLR2) in the activation of the innate immune response to dengue and the clinical outcomes." (PMID 35632732, 2022). "In the present study it was observed that VDR gene and TLR 4 gene polymorphisms are associated with dengue virus infection in north Indian population but no such association was observed with TLR2 polymorphism." (PMID 34602778, 2021). "In a previous study, a differentially expressed TLR profile was reported in children with severe dengue, wherein increased expression of TLR7 and TLR4 transcript variant 3 (TLR4R3) and decreased expression of TLR1, TLR2, TLR4R4, and TLR4 cofactor CD14 were observed." (PMID 34603272, 2021). "We proceeded to investigate whether TLR2-engagement is a PAN-dengue phenomenon." (PMID 32576819, 2020).
dengue (continued). "When dengue patients were classified according the clinical outcome, a higher expression level of TLR2 was seen in DHF patients when compared to DF patients." (PMID 23469297, 2013). "We reported that monocytes from dengue patients, as well as DENV-2-infected monocytes in vitro, exhibit increased expression of TLR2 and TLR4, which supports the involvement of TLR activation during infection." (PMID 41012652, 2025). "The occurrence of NETs in dengue is thought to be mediated by platelet extracellular vesicles, which in turn promote signalling via C-type lectin domain containing 5 A (CLEC5A) and Toll-like receptor 2 (TLR2)." (PMID 39066252, 2024). "In 2010, we reported that CD14 (+) monocytes expressing TLR2 and TLR4 were increased in peripheral blood from mild dengue patients compared to severe ones." (PMID 35632732, 2022). "As TLR2 is partner of TLR6, its expression by PBMC during dengue virus infection was also investigated." (PMID 26226614, 2015). "In this study we examined the expression level of TLR2, 3, 4 and 9 and of the co-stimulatory molecules CD80 and CD86 in dengue patients experiencing distinct disease manifestations." (PMID 23469297, 2013). "In addition, CD14(+) monocytes expressing TLR2 and TLR4 were increased in peripheral blood from mild dengue patients compared to in that of patients with severe dengue, suggesting the protective role of TLR2 and TLR4 in this setting." (PMID 34603272, 2021). "This up-regulation suggested the possible involvement of TLR2 and TLR6 in dengue virus infection." (PMID 26226614, 2015). "Therefore, we evaluated the expression levels of TLR2, TLR3, TLR4 and TLR9 in mDCs, pDCs and monocytes of dengue patients, and compared them to the HCs." (PMID 23469297, 2013). "However, whilst TLR2 expression significantly increased in IM and NM subsets from acute dengue patients, TLR7 was not." (PMID 40934228, 2025). "Unlike in mDCs, in pDCs of dengue patients, only TLR2 expression was stimulated." (PMID 23469297, 2013).
dermatitis (12 papers, 2014 to 2025). An inflammatory process affecting the skin. "Although TLR2 signaling is known to play a critical role in the induction of proinflammatory cytokines by immune cells, such as dendritic cells (DCs), macrophages, and monocytes, TLR2 deficiency unexpectedly exacerbated psoriasiform skin inflammation." (PMID 33202847, 2020). "Although TLR2 signaling has been known to induce inflammatory cytokines and immune responses, TLR2 deficiency unexpectedly exacerbated psoriasiform skin inflammation." (PMID 33202847, 2020). "In a fetal autopsy study, Kim and colleagues demonstrated fetal skin inflammation and TLR-2 regulation in association with microbial invasion of the amniotic cavity, concluding that dermatitis is a component of the FIRS." (PMID 25520716, 2014). "Bacterial products, including lipoprotein of the cell wall known as lipoteichoic acid (LTA), might play a role in skin inflammation caused by staphylococci and can act as an agonist for Toll-like receptor 2 (TLR2)." (PMID 37834183, 2023). "On the other way, the other study suggested that innate TLR2 signals convert transient T helper 2 cell-mediated dermatitis into persistent inflammation, as seen in chronic atopic dermatitis, through IL-4-mediated suppression of IL-1035." (PMID 35715478, 2022). "To examine the role of TLR2 during psoriasiform skin inflammation, we first applied imiquimod cream on mouse back skin and ear, and investigated the clinical and histopathological features of WT and TLR2 KO mice." (PMID 33202847, 2020). "Finally, adoptive transfer of Tregs from wild-type mice reduced imiquimod-induced skin inflammation in TLR2 KO mice." (PMID 33202847, 2020). "Indeed, TLR2 activation together with IL-4R signaling transfers acute Th2-driven dermatitis (48 h before dermatitis resolution) into long-lasting skin inflammation (14 days) with enhanced expression of the Th1 cytokine IFN-γ." (PMID 26217343, 2015). "Importantly, mRNA levels of Foxp3, IL-10, and TGFβ were significantly decreased in TLR2 KO mice compared with WT mice, suggesting that downregulation of Tregs and impaired IL-10 production in TLR2 KO mice increased Th1 cytokine mRNA levels and exacerbated the imiquimod-induced skin inflammation." (PMID 33202847, 2020). "Propionibacterium acnes in the skin activate toll-like receptor-2 (TLR-2) and promote the secretion of inflammatory factors such as IL-6, IL-8, and TNF-α, thereby inducing skin inflammation." (PMID 36817115, 2022). "Adoptive transfer of Tregs from WT mice, but not from TLR2 KO mice, significantly attenuated skin inflammation after imiquimod treatment compared to PBS-injected TLR2KO mice." (PMID 33202847, 2020).